CXCR2 (C-X-C motif chemokine receptor 2)
Diseases named in the same sentence as CXCR2 in open-access papers (continued):
Sharing a sentence is not in itself a finding about the gene and the disease.
Sepsis (continued). "The same was observed when IL-33, the cytokine favoring neutrophil CXCR-2-dependent infiltration during sepsis, was blocked by a neutralizing antibody (data not shown)." (PMID 33673387, 2021). "Multilevel mixed model analysis examining the longitudinal correlations between the percentages of CD64-positive neutrophils, CCR2-positive neutrophils, CXCR2-negative neutrophils, apoptotic, and NETosis and sepsis status† (n = 30)." (PMID 33424860, 2020). "The daily percentages of CD64-positive neutrophils, CCR2-positive neutrophils, CXCR2-negative neutrophils, apoptosis, and NETosis stratified by sepsis status† (n = 30: septic shock = 19, infection = 11)." (PMID 33424860, 2020). "Interestingly, the altered expression patterns and functions of CXCR2 and CCR2 seen during sepsis are driven by TLR activation in neutrophils." (PMID 30931316, 2019). "Sequence comparison of target receptors for some of these missing sepsis proteins between human and G. gallus showed relatively high conservation (Percent Positive Residues: CXCR1 76.3%, CXCR2 76.5%, C5aR 57.6%) which would argue against the latter possibility." (PMID 26606420, 2015). "However, unlike the CXCR2+ subpopulation, these cells presented mature and immunosuppressive phenotypes and are very likely to be the major regulators of sepsis‐induced lung injury." (PMID 39887584, 2025). "This network uncovered regulatory interactions among genes like MPO, CXCR2, ITGAM, SPI1, SPI1 and EP300, suggesting these TFs may participate in sepsis-related immune responses and inflammatory regulation by modulating the transcriptional activity of core genes." (PMID 41259376, 2025). "In addition, IL-1R2 expression is minimal in cluster 1 and 3 under health and sepsis condition, which co-expressed with Fcgr1and Tim4 but lack of Cxcr2, identified as resident tissue macrophages in the heart." (PMID 41293423, 2025). "Together with the results from CLP sepsis mice, we considered CD274+IL1RN+ mature neutrophils to be immunosuppressive effector cells in the lung environment during sepsis‐induced immunosuppression, which can transition from intermediate‐state CXCR2+ neutrophils." (PMID 39887584, 2025). "The direct effects of PGE2 on sepsis-related ALI in CLP mice were also determined, and the results showed a reduction in NET formation, trafficking of neutrophils from bone marrow to the circulation and lung tissues, and decreased expression of CXCR2 and ROS in peripheral blood neutrophils." (PMID 37533081, 2023). "Additionally, we also identified a negative correlation between CXCR2 and Wip1 in human neutrophils during sepsis." (PMID 28878779, 2017). "The cystathionine b‐synthase and cystathionine g‐lyase (CSE) enzymes, which help to synthesize hydrogen sulphide (H2S) from l‐cysteine, have also been suggested to act as a negative feedback regulators in the development of sepsis by regulating neutrophil CXCR2 expression." (PMID 28244690, 2017). "Besides, the relative composition of CXCR2+ N00 and CD274+IL1RN+ N02 was also increased in immunosuppressive sepsis BALF, indicating that the N00 and N02 neutrophil subpopulations might be more crucial to sepsis‐induced immunosuppression than other subpopulations." (PMID 39887584, 2025). "The sepsis group and non-infected group each had only 1 DEFA1 and 1 ALPL and IL8RB/CXCR2 score that was abnormal and changing (chi-square p < 0.05 more severe sepsis vs sepsis+uninfected)." (PMID 41385588, 2025). "Given the absence of any differences between sepsis and SIRS in PMN blood counts and their proportions in both HD and LD granulocytes, PMNs appear to express lower levels of CXCR2 and CEACAM4 in sepsis than SIRS." (PMID 39434093, 2024). "In contrast to our findings on CXCR2 surface level, our study fails to demonstrate the changes of CD64 and CCR2 surface levels as sepsis-related." (PMID 33424860, 2020).
prostate carcinoma (65 papers, 2008 to 2025). A carcinoma that arises from epithelial cells of the prostate gland. "The stroma-derived CCL2-promoted proliferation and CXCL12-mediated invasion were both amplified in PTEN-deficient prostate cancer due to the abnormal activation of the IL-8/CXCR2 signaling pathway." (PMID 41155662, 2025). "CXCR2 expression has been implicated in prostate cancer lineage plasticity and neuroendocrine transformation in the setting of resistance to potent androgen receptor inhibition and is normally expressed on tissue resident neuroendocrine cells." (PMID 38324085, 2024). "WNT4 located in 1p36 and the induction of WNT4/TCF7L1 resulted in increased malignancy in prostate cancer that was linked to dysregulation of androgen receptor signalling and activation of the IL‐8/CXCR2 pathway." (PMID 37378426, 2023). "Our results suggest that induction of WNT4/TCF7L1 results in increased NED and malignancy in prostate cancer that is linked to dysregulation of androgen receptor signaling and activation of the IL-8/CXCR2 pathway." (PMID 34799554, 2021). "In addition, the CXCL5/CXCR2 axis has been implicated in cancers, in which it can facilitate tumor progression and metastasis, including prostate cancer." (PMID 39765818, 2024). "To explore this, we orthotopically implanted RM-1 prostate cancer cells or RM-1 cells overexpressing CXCR2 into the prostates of C57BL/6 mice." (PMID 41163221, 2025). "For example, CXCL2 promotes neutrophil recruitment and inflammatory responses via the CXCR2 axis, and inhibiting CXCR2 can alleviate myeloid inflammation and reverse treatment resistance in prostate cancer." (PMID 40564191, 2025). "Mechanistically, we observed that IL-8/CXCR2 signalling promotes prostate cancer cells to secrete ω−3/6 PUFAs, which are taken up by macrophages via CD36 and contribute to M2 polarization, thus fostering an immunosuppressive TME." (PMID 41163221, 2025). "Together, these findings underscore the multifaceted therapeutic potential of CXCR2 inhibition in overcoming immune evasion, metabolic reprogramming, and treatment resistance in prostate cancer." (PMID 41163221, 2025). "Aberrant activation of CXCR2 has been reported in multiple cancers, including neuroblastoma (NB), melanoma, colon, breast, ovarian, pancreatic, and prostate cancers." (PMID 41155662, 2025). "In a murine model of prostate cancer, the introduction of a CXCR2 antagonist or the infusion of bone marrow-derived CXCR2 Knockout macrophages resulted in a striking decrease in tumor growth." (PMID 40124384, 2025). "Among the various cytokines and chemokines present in the TME, IL-8 and its receptor CXCR2 have drawn considerable attention for their roles in prostate cancer biology." (PMID 41163221, 2025). "CXCR2 expression is upregulated in a number of tumor types, including prostate cancer, colorectal cancer (CRC), and non–small-cell lung cancer (NSCLC), and expression of CXCR2 and its ligands is associated with poor patient prognosis." (PMID 38324085, 2024). "Recently, several chemokines, including CXCL8 and its receptors (CXCR1 and CXCR2), have been shown to impact the development and progression of prostate cancer." (PMID 39766038, 2024). "While it is accepted that CXCR2 is a highly neutrophil-specific protein, there are reports that non-neutrophil cells including glomerular endothelium, sensory neurons, and neuroendocrine cells in human prostate cancer also express CXCR2." (PMID 38786066, 2024). "Recent studies have underscored the crucial role of CXCR2 in prostate cancer metastasis, particularly as to bone, a common site for prostate cancer spread." (PMID 39765818, 2024). "This review explores the role of interleukin-8 (IL-8) and its receptors, CXCR1 and CXCR2, in prostate cancer." (PMID 39199570, 2024). "Recent studies indicated that several CXCR2 antagonists have promise for the reduction of tumor growth and metastasis in prostate cancer." (PMID 39765818, 2024).
prostate carcinoma (continued). "This review delves into the intricate roles of interleukin-8 (IL-8) and its receptors, CXCR1 and CXCR2, in prostate cancer (PCa), particularly in castration-resistant (CRPC) and metastatic CRPC (mCRPC)." (PMID 39199570, 2024). "In models of different tumours, including prostate cancer, CXCR2 inhibition blocks the recruitment of tumour-infiltrating PMN-MDSCs leading to tumour suppression." (PMID 37844613, 2023). "In the mouse prostate cancer RM-9 model, CXCR2 blockade abolished the RT-induced increases of neutrophil in the tumor." (PMID 38067390, 2023). "Nagaya and co-workers identified higher expression of the CXC chemokine signaling genes, including CXCL1, CXCL3, CXCL6, CXCR1 and CXCR2 in prostate cancer bone metastases." (PMID 35328625, 2022). "First, we showed that the CXCL5 receptor, CXCR2, which was reported to be expressed in aggressive prostate cancer epithelial cells (GS ≥ 8 and CRPC patients), was also expressed in our spontaneous PRAD model as well as PC3 cells." (PMID 35853880, 2022). "Chronic hypoxia elevated the expression of CXCR1 and CXCR2 in prostate cancer cells and then CXCRs promoted the secretion of IL-8." (PMID 36452497, 2022). "The expressions of CXCR2 and its ligands are elevated during oxaliplatin treatment in prostate cancer." (PMID 33814009, 2021). "ADT induced the secretion of WNT4 which upon engagement of TCF7L1 in prostate cancer cells, enhanced IL-8 and CXCR2 expressions." (PMID 34799554, 2021). "In a murine model of prostate cancer, administration of a CXCR2 antagonist or infusion of bone marrow-derived CXCR2 KO macrophages led to a reduction in tumor growth and a reprogramming of TAMs to a pro-inflammatory, M1 phenotype." (PMID 34944914, 2021). "Gene Set Enrichment Analysis (GSEA) and enzyme-linked immunosorbent assay (ELISA) were also used to evaluate the expression of CXCR2 in prostate cancer (PCA)." (PMID 34692853, 2021). "CXCL5 secreted from prostate cancer cells attracts MDSCs expressing CXCR2 in a mouse model of prostate cancer." (PMID 30736371, 2019). "Our prior studies demonstrated that silencing of PTEN expression increased the transcription and secretion of CXCL8 and increased gene expression of the receptors CXCR1 and CXCR2 in prostate cancer cells." (PMID 24970800, 2014). "Beside their elevated expression in PTEN-deficient prostate cancer cells, CXCR1 and CXCR2 are also expressed on vascular endothelial cells, monocytes and fibroblasts." (PMID 24970800, 2014). "Our previous study demonstrated that interleukin-8 (IL-8), a cytokine potentially involved in androgen-independent growth of prostate cancer, and its receptor CXCR2 are exclusively expressed by neuroendocrine tumor cells in prostate adenocarcinoma." (PMID 23852643, 2013). "Collectively, these findings highlight the link between macrophage polarization and clinical outcomes in prostate cancer, suggesting that combining IL-8/CXCR2 inhibition with existing immunotherapies may offer synergistic benefits for patients." (PMID 41163221, 2025). "Moreover, HDAC inhibitor showed a synergistic antitumor effect with CXCR2 inhibitor by eliminating infiltration of senescence-like neutrophils in prostate cancer." (PMID 40924501, 2025). "Inhibition of IL-8/CXCR2 may disrupt multiple immunosuppressive pathways simultaneously, providing a rationale for therapeutic targeting of the CXCR2 axis in advanced prostate cancer." (PMID 41163221, 2025). "CXCR2 antagonists have been evaluated in preclinical and clinical studies to block the interaction between CXCR2 and its ligands, which can influence the interaction between cancer cells and the tumor microenvironment in prostate cancer." (PMID 39765818, 2024).
prostate carcinoma (continued). "Recent studies have highlighted the role of the CXCR2 axis in prostate cancer metastasis." (PMID 39765818, 2024). "We reasoned that CXCR2 chemokines released by human prostate cancer cells sculpt systemic myeloid inflammation, and that targeting CXCR2 would decrease deleterious myeloid inflammation, reverse ARSI resistance and impart clinical benefit in some patients with mCRPC." (PMID 37844613, 2023). "We next investigated CXCR2 expression on tumour and immune cells in human prostate cancer." (PMID 37844613, 2023). "Interestingly, we have previously reported a hypoxia-induced upregulation of IL8 and CXCR2 gene expression in prostate cancer cells that prolongs survival under this environmental stress." (PMID 35302608, 2022). "For example, CXCR2 signaling promotes the infiltration of myeloid-derived suppressor cells and preferentially sustains pro-tumorigenic M2-differentiation of tumor-resident macrophages within the TME of murine PTEN-deficient prostate cancer's." (PMID 35302608, 2022). "For instance, macrophage reeducation by CXCR2 inhibitors may drive senescence as well as suppress tumor progression in advanced prostate cancer." (PMID 34840630, 2021). "Additionally, Gene Set Enrichment Analysis (GSEA) and enzyme-linked immunosorbent assay (ELISA) were performed to evaluate the expression of CXCR2 in prostate cancer (PCA)." (PMID 34692853, 2021). "In this study, we identified ADT-mediated upregulation of transcription factor 7 like 1 (TCF7L1), which increases the cytokine response and enhances NED of prostate cancer through interleukin (IL)-8/C-X-C motif chemokine receptor type 2 (CXCR2) signaling activation." (PMID 34799554, 2021). "CXCR2 antagonist AZD5069 is currently undergoing clinical evaluation in a prostate cancer setting." (PMID 32743555, 2020). "CXCL3 and its receptor CXCR2 have been recently found overexpressed in prostate cancer cells, prostate epithelial cells and prostate cancer tissues, which may implicate a role for this chemokine in prostate cancer progression and metastasis." (PMID 28533735, 2017). "In addition, activation of both CXCR1 and CXCR2 increases the rate of cell proliferation in prostate cancer." (PMID 27682863, 2016). "Prostate cancer cells cultured under hypoxia, also appear to require NF-κB to upregulate CXCR2 RNA." (PMID 27826243, 2016). "CXCR1 and CXCR2 could stimulate prostate cancer progression through autocrine signaling of cancer cells." (PMID 25990390, 2015). "Furthermore, loss of PTEN function concurrently increased the expression of CXCL8 receptors (CXCR1 and CXCR2), with the resulting elevated autocrine CXCL8 signaling acting to sustain the viability of these PTEN-deficient prostate cancer cells." (PMID 24970800, 2014). "Thus CXCR2 knockout mice have a significantly reduced tumor burden in prostate cancer, murine Lewis lung cancer and renal tumor models when compared to CXCR2 wild-type mice." (PMID 24376747, 2013). "Moreover, we have confirmed that exposure to 5-FU potentiates this level of CXCL8 signaling by concurrently inducing CXCL8 secretion and up-regulating CXCR1 and CXCR2 gene expression in metastatic prostate cancer cells." (PMID 22590561, 2012). "AZD5069 is a novel antagonist of CXCR2, which is shown to inhibit the binding of IL‐8 to CXCR2 specifically and is being investigated for the clinical benefits in combination with Enzalutamide in metastatic castration‐resistant prostate cancer patients (NCT03177187)." (PMID 39015554, 2024). "This study explored the concept that CXCL5 is an antioxidant oncogene through the CXCL5/CXCR2/HO-1 pathway in prostate cancer cells, suggesting that the CXCL5/CXCR2/HO-1 signaling pathway could provide a new strategy for the treatment of oxidative stress in the prostate." (PMID 39765818, 2024).
prostate carcinoma (continued). "Additionally, when CXCR2 expression is increased in prostate cancer cells, the expression of secretory factors such as VEGF, angiogenin, thrombopoietin, oncostatin M, IGF-1, CCL2/MCP-1, CCL22/MDC, and M-CSF is increased, namely factors that are involved in tumorigenesis." (PMID 37108425, 2023). "Interestingly, in our previous work analyzing the effects of dura, which is in close proximity to the vertebral body, on tumor growth, we demonstrated that conditioned media from dural fibroblasts increased the growth, migration, and invasion of prostate cancer through the CXCR2 pathway." (PMID 35476843, 2022). "In addition, CXCL1 could be a diagnostic factor to observe whether high-grade prostate cancer has deteriorated, and the CXCL1/CXCR2 axis has been reported in the glial cells during neuropathic pain." (PMID 34813418, 2022). "Given that functional impairment of PTEN is reported in up to 30% of all primary prostate cancers and that radical RT is a major treatment option for locally advanced high-risk disease, CXCR1/CXCR2-targeted therapeutics may have a significant impact across a large cohort of patients." (PMID 32743555, 2020). "Collectively, these findings indicate that the IL-8/CXCR2 signalling axis plays a key role in modulating TAM infiltration and polarization within the prostate cancer microenvironment." (PMID 41163221, 2025). "Further studies found that inhibition of CXCL8 and its receptor chemokines CXCR1 and CXCR2 promote G1 cell cycle arrest and apoptosis, suggesting that CXCR1 and CXCR2 inhibit tumor progression in prostate cancer by influencing cell proliferation." (PMID 41347146, 2025). "Androgens have been shown to upregulate the expression of CXCR4, CXCR2, CXCR8, and, consequently, Bcl2 proteins through NF-κB-regulated transcription, increasing the metastatic capacity of prostate carcinoma cells." (PMID 39501277, 2024). "Navarixin, one of the potent and selective antagonists of the human CXCR1/CXCR2, is also evaluated in combination with Pembrolizumab in NSCLC participants, castration‐resistant prostate cancer, or microsatellite stable colorectal cancer (NCT03473925)." (PMID 39015554, 2024). "In prostate cancer (PCa), BMAT releases chemokines CXCL1 and CXCL2, which induce osteoclastogenesis through CXCR2 signaling." (PMID 38625510, 2024). "In this study, our objective is to elucidate the function of CXCL5 in human prostate cancer and stromal cells and to investigate the antioxidant characteristics of the CXCL5/CXCR2/HO-1 axis in human prostate cells." (PMID 39765818, 2024). "CXCL5 evinces antioxidant properties by upregulating heme oxygenase-1 (HO-1) to counteract H2O2-induced reactive oxygen species (ROS) in a CXCR2-dependent manner in WPMY-1 and prostate cancer cells." (PMID 39765818, 2024). "The expression of CXCR2, the receptor for CXCL1, is higher in less aggressive prostate cancer lines." (PMID 37108425, 2023). "Furthermore, the interplay between IL-8/CXCR2 signalling, CD47 regulation, and macrophage infiltration has significant clinical implications in prostate cancer." (PMID 41163221, 2025). "Importantly, our findings reveal that IL-8/CXCR2 signalling regulates both the expression and membrane localization of CD47 in prostate cancer cells through palmitoylation, a lipid modification process." (PMID 41163221, 2025). "In the treatment of prostate cancer with oxaliplatin, the expression of CXCL1, CXCL8 and CXCR2 were significantly increased, while CXCR2 inhibitors could enhance the cytotoxicity of oxaliplatin and achieve the combined anti-tumor effect." (PMID 33814009, 2021). "The overexpression of CXCL3 and its receptor CXCR2 promoted the proliferation and migration of cancer cells by regulating the expression of genes, including ERK, BAX, TP73, and NDRG3, which enhance the oncogenic potential of prostate cancer." (PMID 30686982, 2018).